CD5 (CD5 molecule)
Diseases named in the same sentence as CD5 in open-access papers (continued):
Sharing a sentence is not in itself a finding about the gene and the disease.
hepatoma (1 paper, 2013). "CD5 was displayed by HCV-prone T cell lines, primary T cells and PBMC, but not by non-susceptible T and hepatoma cell lines, while CD81 in all cell types except HepG2." (PMID 23626783, 2013). "In regard to the TJ proteins, CLDN-1 protein was detected only in HCV-resistant PM1 T cells (∼30% of the signal displayed by Huh7.5 cells) and in HepG2 hepatoma cells (∼170% of the signal identified in Huh7.5), and at a lower level (∼25%) by control HEK-293 cells transfected with CD5." (PMID 23626783, 2013). "Furthermore, PHH and HepG2 cells did not transcribe this gene, while hepatoma Huh7.5 cells displayed CD5 mRNA at the mean level of 9.6×103± SEM 1.6×103 copies/μg total RNA." (PMID 23626783, 2013).
Hepatosplenomegaly (1 paper, 2021). Simultaneous enlargement of the liver and spleen. "IPI, NE, MYC, hepatosplenomegaly, and age proved to be adverse factors for the survival of CD5+ patients." (PMID 34804942, 2021).
Hypogammaglobulinemia (1 paper, 2024). "Hypogammaglobulinemia, associated with compromised T- and nonclonal CD5- B cell functions, significantly impacts infection frequency and survival rates in patients with CLL." (PMID 38715775, 2024).
IgA vasculitis (1 paper, 2021). "In patients with IgA vasculitis that had impaired Breg function, the treatment with glucocorticoid prednisolone, promoted an increase in CD5+CD1d+, CD5+CD1d+ IL-10+, and IL-10+ B cell subsets, accompanied by an increase in the serum IL-10 concentration." (PMID 34950041, 2021).
Insulin resistance (1 paper, 2024). Increased resistance towards insulin, that is, diminished effectiveness of insulin in reducing blood glucose levels. "For this reason, in our study, the percentage of B lymphocytes that have a CD5+ cluster—which is associated with the onset of metabolic syndrome and insulin resistance—was examined." (PMID 39452932, 2024).
intestinal infections (1 paper, 2016). "B-1 cells are enriched in the pleural and peritoneal cavities where pulmonary or intestinal infections usually occur, which consist of two functionally specialized subpopulations, CD5+ B-1a and CD5- B-1b cells." (PMID 26735852, 2016).
jaw cysts (1 paper, 2026). "UTP20, AATF, and CD5 may represent potential candidate biomarkers associated with jaw cysts." (PMID 42175431, 2026). "The identified 6 proteins, namely CD79A, CD5, KRR1, UTP20, AATF, and WDR43 - may be closely associated with the pathogenesis of jaw cysts." (PMID 42175431, 2026).
laryngeal tumor (1 paper, 2024). "Postoperative IHC results of the laryngeal tumor were as follows: CD20 (+), CD79a (+), CD3 (−), CD10 (−), Bcl-2 (+), CD5 (−), Cyclin D1 (−), and CD23 (−)." (PMID 39290501, 2024). "Postoperative immunohistochemistry (IHC) results of the laryngeal tumor were as follows: cluster of differentiation 20 (CD20) (partial +), CD79α (diffuse +), CD5 (−), CD10 (−), CyclinD1 (−), B-cell lymphoma 2 (Bcl-2) (+), Bcl-6 (−), and Epstein Barr encoding region (EBER) in situ hybridization (−)." (PMID 39290501, 2024).
latent infection (1 paper, 2025). "B-1 cells are the predominant B cells to foster latent infection in the peritoneal cavity and are subdivided into B-1a (CD5 neg) and B-1b (CD5 pos) cells based on CD5 expression, with B-1b cells harboring most, if not all, of the latent MHV68 compared to B-1a cells." (PMID 41335125, 2025).
liver cancer (1 paper, 2022). An epithelial or non-epithelial malignant neoplasm that arises from the liver. "In addition, there were 30 CD8 T cell-related genes associated with liver cancer prognosis [e.g., CD5 molecules like CD5L, EOMES, and CST7]." (PMID 34980144, 2022).
malnutrition (1 paper, 2021). Inadequate nutrition resulting from poor diet, malabsorption, or abnormal nutrient distribution. "The results of subgroup analysis showed that a significant deterioration of OS in GCB, CD5 positive, and BCL-6 positive groups with malnutrition identified by PNI." (PMID 34729103, 2021).
Merkel cell carcinoma (1 paper, 2023). "Furthermore, the relationship between CD5 and neuroendocrine lineages across different organs is of interest, as Merkel cell carcinoma, a cutaneous neuroendocrine carcinoma, can express this molecule." (PMID 38201543, 2023).
metastatic tumor (1 paper, 2016). "CD5 is specific to the thymic epithelial cell, and metastatic tumor is excluded." (PMID 27822875, 2016).
mucoepidermoid carcinoma (1 paper, 2025). A carcinoma morphologically characterized the presence of cuboidal mucous cells, goblet-like mucous cells, squamoid cells, cystic changes, and a fibrotic stromal formation. "CD5 also remained significantly associated with OS when including all cases except small cell carcinomas and mucoepidermoid carcinomas (i.e., only non-neuroendocrine, non–salivary gland-type tumors included; HR = 0.15, 95% CI: 0.02–0.56, p = 0.003)." (PMID 40242668, 2025).
myasthenia (1 paper, 2021). "Of note, in the current series, one patient (#4) not only had myasthenia but also showed a lack of CD5 expression." (PMID 34069513, 2021).
myasthenia gravis (1 paper, 2017). Myasthenia gravis (MG) is a rare, clinically heterogeneous, autoimmune disorder of the neuromuscular junction characterized by fatigable weakness of voluntary muscles. "CD19+CD5+CD1d+ Bregs expression and interleukin (IL)-10 and transforming growth factor (TGF)-β1 secretion in isolated B cells in patients with myasthenia gravis (MG) (n = 10) as compared to healthy controls (HCs) (n = 10)." (PMID 28265257, 2017).
ocular adnexal lymphoma (1 paper, 2013). A non-Hodgkin lymphoma arising from the conjunctiva, lacrimal gland, lacrimal drainage apparatus, eyelids, or other orbital tissues around the eye. "However, CD5 and cyclin D1 are two markers that can lead to diagnostic pitfalls that could drastically impact patient care within the realm of orbital and ocular adnexal lymphomas." (PMID 23691402, 2013).
pancreatic adenocarcinoma (1 paper, 2025). "No immunohistochemical studies of CD5-positive lymphocytes in pancreatic adenocarcinomas could be identified in the medical literature." (PMID 40075893, 2025).
pancreatic cancer (1 paper, 2021). "In addition, CD5 expression was clearly higher in pancreatic cancer tissues than in the normal adjacent tissues by IHC." (PMID 33824474, 2021).
periodontal disease (1 paper, 2026). "This cross-sectional study examined differential subsets of circulating CD5+ B cells as potential systemic biomarkers of early periodontal disease." (PMID 41708693, 2026).
prostate lymphoma (1 paper, 2018). A rare non-Hodgkin or Hodgkin lymphoma that arises from the prostate gland. "CK, CD3, CD21, CD23, CD10, Bcl6, MUM1, Blc2, CD5, CyclinD1 and Ki-67 are the most common immunohistochemical combinations for prostate lymphoma." (PMID 29308052, 2018).
psoriatic arthritis (1 paper, 2022). Joint inflammation associated with psoriasis. "However, recent unpublished results from a collaborative study show seasonality phenomena in Cd5-/- mice upon mannan-induced psoriatic arthritis induction (Merino R and Merino J, University of Cantabria, Spain)." (PMID 36211446, 2022).
pulmonary lymphoma (1 paper, 2026). "Bronchoalveolar lavage (BAL) flow cytometry demonstrated an aberrant CD4-predominant T-cell population (CD4:CD8 ratio 9.2:1) with loss of pan-T cell antigens CD5 and CD7, providing early evidence of pulmonary lymphoma involvement and prompting expedited hematological evaluation." (PMID 42212304, 2026).
Richter syndrome (1 paper, 2023). Transformation of chronic lymphocytic leukemia into aggressive non-Hodgkin's lymphoma, usually diffuse large B-cell lymphoma (immunoblastic or centroblastic variant). "Therefore, it is recommended to routinely examine CD5 and Cyclin D1 for the differential diagnosis of DLBCL, blastoid/pleomorphic variant MCL, DLBCL-type Richter syndrome and primary CD5-positive DLBCL, which is more aggressive." (PMID 37182167, 2023).
salivary carcinomas (1 paper, 2022). "There is no data regarding the frequency of CD5 and CD117 expression in salivary carcinomas and this issue should be investigated in future studies." (PMID 34807356, 2022).
skin tumor (1 paper, 2022). "Though STAT3 activation and CD5+ B cell proportion are correlated with poor outcomes in B16 skin tumor cell lines, adoptive transfer of activated B cells in tumor cell inoculated mice leads to slower tumor growth." (PMID 36033455, 2022).
Still’s disease (1 paper, 2024). "Regarding B-cell subsets with regulatory properties, we noted a decline in the level of peripheral blood CD5-expressing B cells in Still’s disease." (PMID 38392193, 2024).
Streptococcus pneumonia (1 paper, 2019). "Numerous infection models have reported CD5- ‘B-1b’ cell responses after infection, including studies on mice infected with Streptococcus pneumonia and S. typhimurium." (PMID 31433296, 2019).
T-cell deficiency (1 paper, 2023). "Notably, no clinical manifestations or conditions associated with CD5+ T-cell deficiency were identified during the subsequent follow-up assessments." (PMID 38143760, 2023).
tongue tumors (1 paper, 2023). "We determined that subcutaneous tumors contained a higher frequency of B cells that were PD-1+ and IgM+CD5+ compared to B cells in tongue tumors." (PMID 37035195, 2023). "Representative plots of CD19+ gated cells show distinct populations for PD-1+ B cells and IgM+CD5+ B cells in subcutaneous tumors which are less distinct in tongue tumors." (PMID 37035195, 2023).
Warthin’s tumor of (1 paper, 2025). "We describe the incidental discovery of a CD5-positive monoclonal B-cell population within a classic Warthin’s tumor of the parotid gland in a 72-year-old woman who presented with a painless, slow-growing left parotid mass." (PMID 41393737, 2025). "Overall, the morphologic and immunophenotypic features were most consistent with Warthin’s tumor with focal involvement by a low-grade CD5-positive B-cell lymphoproliferative disorder, favoring MBL, CLL-type." (PMID 41393737, 2025). "Core needle biopsy and subsequent parotidectomy demonstrated typical histologic features of Warthin’s tumor along with a low-level (8%-9%) CD5- and CD23-positive B-cell population consistent with chronic lymphocytic leukemia (CLL)-type monoclonal B-cell lymphocytosis (MBL)." (PMID 41393737, 2025).
Wilson disease (1 paper, 2018). A very rare inherited multisystemic disease presenting non-specific neurological, hepatic, psychiatric or osseo-muscular manifestations due to excessive copper deposition in the body. "Our case represents the occurrence of IVLBCL with CD5-positivity in a patient with Wilson's disease, diagnosed at autopsy demonstrating the challenging nature of diagnosing IVLBCL." (PMID 30643658, 2018).
tumor (304 papers, 2005 to 2026). "We further reveal that the tumor cells resisting iCAR-M killing show reversible CD5 loss mediated by iCAR-M trogocytosis." (PMID 41943855, 2026). "The reported loss of CD5 expression upon Richter’s transformation reflects the current state of knowledge, again showing that the model can reproduce known behaviors of the tumor." (PMID 40938978, 2025). "CD5 is expressed on normal T cells and the surface of hematologically malignant cells and can cause on-target and off-tumor effects." (PMID 41050660, 2025). "Nonetheless, when NK cells are engineered with a CAR recognizing antigens also expressed on normal cells, such as CD5, there remains a risk of on-target off-tumor effects, which requires careful CAR design." (PMID 41050660, 2025). "CD5 can be expressed in 5%–10% of DLBCL, NOS, and CD5‐positivity is believed to be associated with an inferior outcome of this tumor." (PMID 37081786, 2023). "The current study provides evidence for a critical role for CD5 in regulating PD-1 expression in tumor-associated CD8+ T cells and suggests a therapeutic approach to sensitize T cell to immune checkpoint blockade." (PMID 33584650, 2020). "In that respect, in a mouse model of pancreatic ductal adenocarcinoma, treatment with BTK inhibitor induces a reduction in tumor growth which was associated with a depletion or decreased presence of IgMloCD23+CD5− follicular and IgMlo CD23− memory B cells." (PMID 31086070, 2019). "Nevertheless, previous reports on CD5-deficient mice provide evidence that sole abrogation of CD5 signaling leads to enhanced anti-tumor response." (PMID 29296231, 2017). "PTEN encoding a tumor suppressor antagonizing the PI3K/AKT signaling was significantly downregulated in CD5+ GCB-DLBCL." (PMID 25760242, 2015). "The pathologic features showed blastoid variant of MCL and flow cytometry showed that the tumor cells were CD5−, CD19+, CD20+, FMC-7+, CD23−, and lambda light chain restricted." (PMID 26347832, 2015). "The whole tumor cell population revealed a CD5 antigen loss and a weak and obviously only cytoplasmic reactivity for βF1." (PMID 22497840, 2012). "Additionally, CD5#14 CAR demonstrated significantly higher binding to CD5+ target cells, contributing to its superior lysis activity but also increasing the risk of on-target off-tumor toxicity." (PMID 41050660, 2025). "This could mechanistically explain why, during CLL transformation to RS, most tumor cells show a loss of CD5 expression as observed in our model and in the CD5 expression of our FFPE patient cohort." (PMID 40938978, 2025). "Notably, 94.3% of malignant CD4+ T cells in tumor stage MF lesions exhibited complete CD5 loss compared to only 76.6% in patch-plaque MF lesions, suggesting antigen escape in tumor stage disease." (PMID 41226451, 2025). "If significantly correlating with response, CD5 could indeed be the desired biomarker to amend or even overcome the insufficient predictive significance of immune infiltration, PD-L1 expression or tumor mutational burden." (PMID 37230972, 2023). "A causal role for CD5 in T cell activation, supported by evidence presented here and by us previously, forms the basis to propose targeting of CD5 as a therapeutic intervention to enhance anti-tumor immunity." (PMID 33584650, 2020). "The mechanism regulating expression in vivo is not well understood and it is difficult, with our present level of understanding, to determine the reasons underlying our observation of CD8+ T cells with reduced CD5 in the tumor microenvironment compared to T cells from lymph node and spleen." (PMID 33584650, 2020). "Finally, CD5-deficient mice engrafted with B16-F10 melanoma cells had slower tumor growth compared to wild type C57BL/6 mice." (PMID 29701673, 2018). "CD5+ B cells have also been implicated in the suppression of anti-tumor immunity in humans through activation of Stat3, a transcription factor that may be involved in production of IL-10." (PMID 27437104, 2016).
tumor (continued). "In contrast, the retrieved iCAR-Ms from tumor cell co-culture retained tumoricidal activity on new tumor cell expressing CD5." (PMID 41943855, 2026). "CD5 expression was significantly reduced in malignant CD4 T cells from tumor-stage MF lesions compared to patch/plaque MF lesions." (PMID 41226451, 2025). "Our results suggest a promising avenue for optimized CD5 CAR-NK cell therapy to manage T cell malignancies while minimizing off-tumor effects." (PMID 41050660, 2025). "Next, we assessed CD5 expression in all cell clusters from healthy control, tumor-stage, and patch/plaque stage MF lesions." (PMID 41226451, 2025). "Based on these findings, we identified #11 as the optimal scFv to minimize on-target off-tumor toxicity for OptiCAR-NK development and focused on further optimizing the expression of #11 CD5 scFv in subsequent experiments." (PMID 41050660, 2025). "HCC‐mediated CCL20 production has been shown to recruit CCR6+CD5+ B cells, promoting angiogenesis and thus facilitating tumour growth." (PMID 40913253, 2025). "Downregulation of CD5 positive lymphocytes on the tumor immune microenvironment enhances antitumor T cell activity." (PMID 40075893, 2025). "We utilized 5 patch/plaque MF skin biopsies (majority from early-stage patients), 8 MF tumor biopsies (all from advanced-stage patients), and 8 healthy control biopsies to evaluate lesion-specific CD5 gene expression on CD4 T cells." (PMID 41226451, 2025). "Immunohistochemically, the tumor cells were strongly and diffusely positive for CD5, CD117, P63, CK5/6, and P40, with additional positivity for synaptophysin (Syn) and INSM1." (PMID 41476594, 2025). "In subgroup analysis, patch/plaque stage MF biopsies showed higher expression of CD5 in CD4 T cells than tumor stage MF biopsies." (PMID 41226451, 2025). "Optimization of scFv and CAR expression levels (OptiCAR-NK) enabled selective recognition of CD5+ malignant T cells while maintaining strong anti-tumor activity with minimal toxicity." (PMID 41050660, 2025). "Here, we aimed to develop optimized CD5 CAR-NK cells (OptiCAR-NK) to achieve potent anti-tumor activity with minimized off-tumor toxicity." (PMID 41050660, 2025). "The observed decrease in CD5 expression in tumor-stage MF lesions aligns with earlier findings that progressive surface antigen loss is a mechanism of immune evasion and treatment resistance in CTCL." (PMID 41226451, 2025). "Further, higher TIL density (10% increments) was associated with high levels of tumor markers (CD3, CD4, CD5, CD8) and improved prognosis." (PMID 39507608, 2024). "For instance, it has been demonstrated that chemokine (C-C motif) ligand 20 (CCL20) derived from tumor cells interacts with chemokine receptor 6 (CCR6) highly expressed by CD19+ CD5+ B cells, potentially enhancing angiogenesis and promoting HCC development." (PMID 38791916, 2024). "CD5 has been shown to be integral to the native antitumor response as a negative regulator of human dendritic cells and tumor infiltrating lymphocytes." (PMID 39410047, 2024). "Supporting our findings in the Pdcd1−/− mice, where CD5 expression was elevated in the splenic CD8+ T cells, a recent report showed that blocking CD5 together with PD-1 substantially enhanced survival and tumour cell killing." (PMID 39471840, 2024). "Immunophenotypically, tumor cells have a mature B-cell phenotype and frequently express IgM and IgD but typically lack CD5 and CD10." (PMID 38535060, 2024). "In summary, the inflamed subtype of HCC exhibited a notable presence of CD19+ cells accompanied by significant CD5+ and CD1d+ expression in the tumor area." (PMID 39611128, 2024). "CD5+ and CD1d+ cells were abundant and spatially distributed in the different compartments of the tumor." (PMID 39611128, 2024).